CYP1A1 (cytochrome P450 family 1 subfamily A member 1)
Diseases named in the same sentence as CYP1A1 in open-access papers (continued):
Sharing a sentence is not in itself a finding about the gene and the disease.
hepatoma (43 papers, 1999 to 2025). "We had previously demonstrated that interfering with CYP1A1 can enhance the killing effect of lenvatinib on hepatoma cells." (PMID 39183447, 2024). "More than three decades ago it was shown in nuclear extracts of murine hepatoma (Hepa1c1c7) cells that methylation in the AHR consensus sequence of the Cyp1a1 enhancer inhibited AHR binding to this site." (PMID 37696456, 2023). "Specifically, studies in mouse hepatoma cells proved PB to be a weak ligand of AhR, as well as an inducer of CYP1A1 and benzo[a]pyrene hydroxylase activity; on the contrary, CYP1A2 was regulated through molecular mechanisms independent from AhR." (PMID 35408925, 2022). "Prothioconazole has been shown to be an inhibitor of expression of the AHR target Cyp1a1 in a mouse hepatoma cell line, while thiabendazole actived a mouse PXR-dependent reporter system in vitro." (PMID 32403288, 2020). "In nuclear extracts from Hepa 1c1c7 mouse hepatoma cells, methylation of Cyp1a1 enhancer inhibited AHR binding to this site." (PMID 31212893, 2019). "Our recent in vitro studies with the active derivative of C2 proved it to have virtually equal potency in inducing CYP1A1 activity to TCDD in a rat hepatoma cell line and exhibit similar modelled binding properties to the ligand binding region of the AHR." (PMID 30893768, 2019). "Another possible regulation of CYP1A1 is through the degradation of its heme group, which has been explored in human hepatoma cell line HepG2 exposed to different heavy metals." (PMID 28105425, 2016). "Previous studies found that administration of ANE to mice stimulates hepatic CYP enzyme activities, but arecoline inhibits the 2,3,7,8-Tetrachlorodibenzo-p- dioxin (TCDD)-induced CYP1A1 expression in hepatoma cells." (PMID 25051199, 2014). "In contrast, lansoprazole, omeprazole, and pantoprazole induced Cyp1a1, Cyp1a2, Cyp2b and Cyp3a in primary human hepatocytes, human liver, human hepatoma cells and rat liver." (PMID 24846271, 2014). "The expression of CYP1A1/2 mRNA and protein was evaluated in human hepatoma cell line HepG2 and in primary human hepatocytes." (PMID 25000292, 2014). "We have previously demonstrated that both harmine and harmaline are capable of inhibiting TCDD-mediated induction of Cyp1a1 in murine hepatoma Hepa 1c1c7 cells." (PMID 23509697, 2013). "Such increased expression of CYP1A1 has also been reported increase the excretion rate of 8-oxoguanine (oxo8Gua) in human hepatoma cell line, a biomarker of oxidative DNA damage." (PMID 21445290, 2011). "Δ9-THC, the psychoactive component of marijuana, has been discussed as a potential AhR ligand due to its ability to induce Cyp1a1 expression in a murine hepatoma cell line." (PMID 21867498, 2011). "Δ9-THC has been discussed as a potential AhR ligand due to its ability to induce Cyp1a1 expression in a murine hepatoma cell line." (PMID 21867498, 2011). "Alternatively, Gharavi and El-Kadi (2005) showed in murine hepatoma cell lines that Cyp1a1 is down-regulated by the proinflammatory cytokines interleukin 1β (Il-1β), IL-6, and tumor necrosis factor α in an AHR-dependent manner." (PMID 19165387, 2009). "The glucocorticoid dexamethasone has been shown to enhance TCDD-induced expression of CYP1A1, in a rat hepatoma and fish hepatocellular carcinoma cell lines." (PMID 19531241, 2009). "We then performed bulk RNA sequencing (RNAseq) on CCL5‐stimulated Huh7 cells and discovered the CCL5/CCR5/CYP1A1 pathway, which may prompt the drug resistance of hepatoma cells to lenvatinib." (PMID 39183447, 2024). "Interestingly, an increased incidence of hepatocellular carcinomas was observed in rodents upon exposure to PBDE 209 as well as increased CYP1A1 mRNA expression levels in Caco-2 cells." (PMID 39200369, 2024). "Difeconazole induces the AHR target gene CYP1A1 in human hepatoma cells." (PMID 32403288, 2020).
hepatoma (continued). "Further, some quinones, including 1,2-NQ and 1,4-NQ, simulate AhR nuclear translocation and induction of cyp1a1 in mouse hepatoma cells in an AhR-dependent manner and the induction could be blocked by an AhR antagonist." (PMID 32526934, 2020). "Prior to more extensive analysis of the specific interactions of these compounds with the AhR, we first confirmed that 1,2-NQ and 1,4-NQ stimulated induction of the AhR-responsive gene CYP1A1/cyp1a1 in human and mouse hepatoma cells, respectively, in a concentration-dependent manner." (PMID 32526934, 2020). "Finally, mRNA expression of CYP1A1, 1B1, 2J2 and 3A4 was established in 6 hepatocellular carcinoma (HCC) and 14 renal cell carcinoma (RCC) tumor biopsies and their healthy tissue counterparts surrounding the tumor." (PMID 24819355, 2014). "Moreover, we reported that both harmine and harmaline inhibited the TCDD-mediated induction of the carcinogen-activating enzyme, CYP1A1 in human hepatoma HepG2 cells through transcriptional and posttranslational mechanisms." (PMID 23509697, 2013). "Finally, we confirmed that harmine and harmaline possess posttranslational modification by which they reduce the CYP1A1 protein stability in human hepatoma HepG2 cells." (PMID 23509697, 2013). "Indeed, in primary rabbit hepatocytes the mycotoxin inhibited CYP1A1 mRNA, while the inductive effect observed in the present study was reported also in primary human hepatocytes, in a rat hepatoma cell line, as well as in vivo in the liver of ducks fed with an AFB1-contaminated diet." (PMID 35878242, 2022). "Carum carvi extracts were also found to inhibit the 2, 3, 7, 8-tetrachloro-dibenzo-p-dioxin-dependent gene expression of cytochrome P450 1A1 in the rat hepatoma cells, therefore it may affect the drugs metabolyzed by CYP1A1 such as chlorzoxazone, theophylline, bufuralol." (PMID 30364115, 2018). "In line, inhibiting HDAC1, either by small molecule inhibitors or by siRNA, increased the constitutive expression of CYP1A1 in human breast MCF-7 or cervical cancer Hela cells, in human HepG2 and in murine Hepa1c1c7 liver carcinoma cells." (PMID 37696456, 2023). "For instance, TCDD induces NQO1 gene expression in human hepatoma cell lines, but antioxidant N-acetyl cysteine (NAC) or CYP1A1 siRNA decreases NQO1 gene induction, indicating that NQO1 induction is controlled by CYP1A1 activity through oxidative stress." (PMID 35204110, 2022). "Since KET induced CYP1A1 mRNA and protein in human hepatoma cells HepG2, we examined a capability of KET to induce CYP1A1 and CYP1A2 mRNA and protein in primary human hepatocytes, a more physiological and metabolically competent cell model." (PMID 25000292, 2014). "PFOS and PFOA were reported to increase the CYP1A1 expression in salmon kidney and liver, and PFOS significantly further increased the TCDD-induced AhR activity in rat Hepatoma cells." (PMID 24629213, 2014). "We also evaluated CYP1A1, CYP1A2, NQO1, and UGT1A1 expression following leflunomide exposure in HepG2 human hepatoma cells." (PMID 20957046, 2010). "Furthermore another study detected gene expression of CYP2E1, including CYP1A1/1A2 in PBMC and the liver from human patients with hepatocellular carcinoma." (PMID 36461118, 2022). "In cultured rat hepatoma cells, 5-methoxy-MBI induced CYP1A1 protein more potently than MBI." (PMID 32874920, 2020). "In murine hepatoma Hepa-1c1c7 cells, GEN dose-dependently inhibited (0.1–20 μg/mL) TCDD-mediated activation of an XRE-driven reporter system, and in human HepG2 cells, GEN (50 μM) repressed the basal and TCDD-dependent expression of CYP1A1." (PMID 31652854, 2019). "Incubation of mouse hepatoma (hepa1c1c7) cells with ginsenosides (Rc, Rh1, PPD, F11) for 4 h increased CYP1A1 mRNA levels, albeit to a lower level than that induced by TCDD, but these data were consistent with the reporter gene induction results and the AhR agonist activity of these ginsenosides." (PMID 23776647, 2013).
prostate carcinoma (33 papers, 2010 to 2026). A carcinoma that arises from epithelial cells of the prostate gland. "Men exposed to pesticides and who have the polymorphism in the CYP1A1 enzyme are at greater risk of developing prostate cancer." (PMID 36908412, 2023). "A worldwide study of rs1048943 in the CYP1A1 gene revealed an association of the G allele with prostate cancer and colorectal cancer in Iraqi population." (PMID 36553620, 2022). "The purpose of this study was to evaluate the relationship between CYP1A1 gene rs1048943 polymorphism and the risk of Iraqi men with prostate cancer." (PMID 31870130, 2019). "Polymorphism RS 1048943 in the CYP1A1 gene is associated with the risk of developing prostate cancer and is possibly one of the most significant factors in its development." (PMID 31870130, 2019). "In this study, we investigated the relationship in the CYP1A1 gene between this polymorphism (rs1048943) and prostate cancer risk." (PMID 31870130, 2019). "Further, a meta-analysis study showed using subgroup analysis that the CYP1A1 GA + GG genotypes were associated with prostate cancer risk in Asians." (PMID 29165164, 2017). "Findings from a previous study suggested that the CYP1A1 GA + GG genotype confers susceptibility to prostate cancer and that individuals with the CYP1A1 GG genotype have a significantly increased risk." (PMID 29165164, 2017). "The second possibility is that this CYP1A1 polymorphism is an independent risk factor for prostate cancer." (PMID 29165164, 2017). "The Indian cohort study confirmed the association of CYP1A1rs1048943 with a lower risk of Prostate Cancer, this finding strongly suggests that CYP1A1 polymorphism may be closely linked to prostate cancer susceptibility." (PMID 31870130, 2019). "In addition, the CYP1A1 GA + GG genotype was associated with prostate cancer in low, moderate, and high HAA intake groups." (PMID 29165164, 2017). "Recent meta-analysis showed a close association between several cytochrome P450 (CYP) 1A1 polymorphisms and prostate cancer risk, suggesting that CYP1A1 may contribute to prostate cancer tumorigenesis." (PMID 27203547, 2016). "In our study, ex-smokers who had quit smoking 7 or more days before surgery combined with never-smokers showed higher CYP1A1 methylation levels compared with current smokers, indicating smoking to be a modifiable risk factor for prostate cancer that is dependent on CYP1A1 expression." (PMID 27203547, 2016). "Currently several clinical trials targeting BCL2 expression in prostate cancer are ongoing; therefore CYP1A1 may be a promising target for prostate cancer treatment since it is closely associated with BCL2 expression." (PMID 27203547, 2016). "In vivo study indicated that vitamin E upregulated CYPs, including CYP1A1 and CYP1B1 which highly expressed in prostate cancer, increased ROS production and led to the mutation of prostate cells." (PMID 33230422, 2020). "The purpose of this study was to determine the impact of HAA intake and genetic polymorphisms in NAT2, CYP1A1, and CYP1A2 on prostate cancer in Japanese men." (PMID 29165164, 2017). "Further, 12(S)-HETE, which is metabolised by the lipoxygenases ALOX12 and ALOX15 and by cytochrome-P450-1A1 (CYP1A1), induces the metastatic spreading of prostate carcinoma cells." (PMID 28013338, 2017). "The increased risk of prostate cancer was observed among individuals with the NAT2 slow acetylator phenotype (OR, 1.65; 95% CI, 1.04–2.61), CYP1A1 GA + GG genotype (OR, 1.27; 95% CI, 1.02–1.59), and CYP1A2 CA + AA genotype (OR, 1.43; 95% CI, 1.03–2.00)." (PMID 29165164, 2017). "The higher basal expression levels of CYP1A1 in prostate cancer tissues led us to examine the functional significance of CYP1A1 in prostate cancer." (PMID 27203547, 2016). "To further understand the precise mechanism of the pro-apoptotic effect on prostate cancer cells induced by CYP1A1 knockdown, we performed array analyses to determine which apoptotic genes are altered due to CYP1A1 in LNCaP cells." (PMID 27203547, 2016).
prostate carcinoma (continued). "CYP1A1 levels are thus increased in prostate cancer and to determine the functional effect of CYP1A1 on cells, we depleted the gene in LNCaP and DU145 by siRNA." (PMID 27203547, 2016). "In summary, we show that CYP1A1 is an important oncogene in prostate cancer that is up-regulated by DNA promoter hypomethylation." (PMID 27203547, 2016). "We utilized 5-aza-deoxycytidine (5-aza-dC) to screen the methylation status of CYP1A1 in prostate cancer cell lines." (PMID 27203547, 2016). "In this study, we demonstrate that prostate cancer has high expression of CYP1A1 through DNA hypomethylation of XRE sites." (PMID 27203547, 2016). "The relative methylation level of CYP1A1 in region B was significantly lower in prostate cancer (18.5 ± 2.1%) than BPH samples (32.1 ± 2.0%; P < 0.001)." (PMID 27203547, 2016). "In this study, we investigated the expression, methylation status, and functional role of CYP1A1 on prostate cancer cells." (PMID 27203547, 2016). "We further identified that the effects of CYP1A1 knockdown on increased apoptosis in prostate cancer cell lines were correlated with reduction of anti-apoptotic BCL2, the primary gatekeeper of the intrinsic (mitochondrial) apoptotic pathway." (PMID 27203547, 2016). "Initially we measured mRNA and protein expression levels of CYP1A1 in 3 prostate cancer cell lines (PC-3, LNCaP and DU145) and as a comparison, measured expression in BPH-1 cells." (PMID 27203547, 2016). "The relative methylation amount of the CYP1A1 promoter in region A was significantly lower in prostate cancer (49.2 ± 1.6%) than in BPH samples (62.5 ± 1.3%; P < 0.01)." (PMID 27203547, 2016). "This study supports an oncogenic role for CYP1A1 in prostate cancer via promoter hypomethylation that is influenced by tobacco smoking, indicating CYP1A1 to be a promising target for prostate cancer treatment." (PMID 27203547, 2016). "Next we investigated the expression of CYP1A1 by immunohistochemical staining in 102 primary prostate cancers, 14 normal prostate and 70 BPH samples obtained from TMAs." (PMID 27203547, 2016). "We then evaluated the association between smoker status and the methylation level of CYP1A1 enhancers in prostate cancer patients." (PMID 27203547, 2016). "AHR is expressed in prostate cancer cells and induces its known target genes CYP1A1 and CYP1B1." (PMID 37077937, 2023). "Among four case-control studies in Japan, one study each for colorectal, stomach, and prostate cancer investigated whether NAT2 acetylation genotype and CYP1A1 and CYP1A2 genotype modify the association between dietary HAA intake and risk of cancer." (PMID 34315542, 2021). "In addition, we found that the NAT2 slow acetylator phenotype, the CYP1A1 GA + GG genotype, and the CYP1A2 CA + AA genotype were associated with increased prostate cancer risk." (PMID 29165164, 2017). "The purpose of our study was to determine whether there was evidence of an association between HAA intake, polymorphisms in NAT2, CYP1A1, and CYP1A2 and prostate cancer risk in Japanese men." (PMID 29165164, 2017). "Therefore DNA hypomethylation of three CYP1A1 XRE sites was more common in prostate cancer than BPH tissues." (PMID 27203547, 2016). "Thus taken together with our results of prostatic tissues and cell lines, these findings strongly suggest that DNA hypomethylation of the CYP1A1 enhancer is a frequent event in prostate cancer and involved in the induction of CYP1A1 expression." (PMID 27203547, 2016). "Since attenuation of CYP1A1 significantly inhibited proliferation of prostate cancer cell lines, we hypothesized that this may be due to apoptosis induction." (PMID 27203547, 2016). "Finally, we knocked the CYP1A1 gene down in prostate cancer cell lines by RNA interference and performed functional analysis to evaluate its biological role in tumorigenesis." (PMID 27203547, 2016).
prostate carcinoma (continued). "While CYP1A1 expression was weak or not detected in most of the normal prostate (0.79 ± 0.11) and BPH (0.57 ± 0.07) tissues, the majority of prostate cancer samples showed much higher CYP1A1 immunoreactivity with an average staining score of 1.82 ± 0.08 (P < 0.001)." (PMID 27203547, 2016). "We determined this by testing the effects of CYP1A1 reduction on prostate cancer cell viability." (PMID 27203547, 2016). "In this study, we assessed whether CYP1A1 levels were elevated in prostate cancer compared to normal prostate or benign prostatic hyperplasia (BPH) using tissue microarray (TMA) of human specimens as well as prostatic cell lines (cancer versus BPH-1)." (PMID 27203547, 2016). "Our study on prostate cancer also supports regulation by methylation as treatment of PC-3, LNCaP, and DU145 with demethylating agent caused an enhanced increase of CYP1A1 expression with dramatic loss of methylation as shown by MSP/USP analyses of the enhancer XRE-1383 site." (PMID 27203547, 2016). "In prostate cancer cells, urolithins (A, B, C, and D) inhibited CYP1B1 activity (a target in prostate cancer chemoprevention) in a dose ranging from 1.15 μM (urolithin A) to 137 μM (urolithin D) whereas higher concentrations were needed for CYP1A1 activity inhibition (12.4–2,907 μM)." (PMID 23781257, 2013). "Thus CYP1A1 is up-regulated in prostate cancer cell lines and tissues." (PMID 27203547, 2016). "On the basis of previous findings linking CYP1A1 to the PI3K-Akt signaling pathway in breast and prostate cancer, we observed that the CYP1A1_I462V mutant increased both total Akt levels and Akt phosphorylation in cells expressing edited CYP1A1 constructs as well as A549I462V cell lines." (PMID 40175891, 2025). "On the other hand, in prostate cancer LNCaP cells that lack H3K4me3 in the CYP1A1 regulatory region, TCDD did not induce CYP1A1 expression." (PMID 37696456, 2023). "Although PCB 153 and 180 are classified in group 3 and considered to be CYP1A1 and CYP2B inducers, our present results showed no positive association between prostate cancer and any PCB congener." (PMID 20435560, 2010). "Tryptophan metabolism was one of the 27 pathways, and the downstream target genes of AhR, CYP1A1 and CYP1B1, were considerably elevated after AhR binding, suggesting that tryptophan metabolism is significantly activated in recurrent castration-resistant prostate cancer." (PMID 40759641, 2025). "Also in human prostate cancer samples, the CYP1A1 enhancer was methylated in 11 out of 30 samples, while no methylation in the CYP1A1 promoter was detected in healthy control tissue." (PMID 37696456, 2023).